HIF1A (hypoxia inducible factor 1 subunit alpha)
Diseases named in the same sentence as HIF1A in open-access papers (continued):
Sharing a sentence is not in itself a finding about the gene and the disease.
acute kidney injury (40 papers, 2012 to 2026). Sudden and sustained deterioration of the kidney function characterized by decreased glomerular filtration rate, increased serum creatinine or oliguria. "Preconditioning refers to exposure to a stimulus to protect organs or tissues before subjection to ischemic injury, and HIF-1α has been implicated as an attractive target pathway for ischemic preconditioning for prevention against acute kidney injury." (PMID 32438631, 2020). "HIF-1 has two faces; although upregulation of HIF-1α is protective in acute kidney injury, long-term hypoxia-driven overexpression is associated with increased kidney fibrosis." (PMID 31007700, 2019). "In the present study, we found that SSR significantly reversed the secretion of IL-1β and downregulated the expression of HIF-1α, c-Myc, and IL-1β proteins in residual renal tissue of rats with renal failure, which may be associated with the improvement of renal function and RIF." (PMID 34211565, 2021). "In another study, TMZ alleviated folate-induced acute kidney injury in mice mainly by stimulating HIF-1α/heme oxygenase-1 (HO-1)." (PMID 39108756, 2024). "Numerous studies proved that the HIF-1α protected against early chronic kidney diseases, acute kidney injuries, cisplatin-induced apoptosis, vascular damage, and impaired circulation in animal and cell lines study." (PMID 37981699, 2023). "Roxadustat pretreatment was anticipated to protect from FA-induced acute kidney injury (AKI) by stabilizing HIF-1α and therefore to strengthen the antioxidation system." (PMID 36843948, 2023). "Although HIF‐1α appears to exert a protective effect on renal damage in acute kidney injury, chronic sustained activation of HIF‐1α in renal tubular epithelial cells has been found to promote epithelial to mesenchymal transition and kidney fibrosis." (PMID 30614190, 2019). "For instance, pharmacological up-regulation of HIF-1α represents a novel strategy in the prevention of acute kidney injury." (PMID 22252226, 2012). "For instance, Panax notoginseng saponins exhibit renoprotection against cisplatin-induced acute kidney injury and lupus nephritis comparable to those of ginsenosides, but act primarily through HIF-1α/mitochondrial pathways and macrophage-derived exosome–mediated autophagy." (PMID 41415561, 2025). "Interestingly, pre-clinical studies have demonstrated that activation of HIF-1α NTAD induced by the PHD inhibitor protects against acute kidney injury (AKI) and chronic kidney disease." (PMID 37225700, 2023). "Furthermore, the upregulation of mitophagy induced by activated HIF-1α/BNIP3 signaling pathways was proved to inhibit apoptosis in acute kidney injury." (PMID 37101593, 2023). "HIF-1a plays a protective role via HIF-1α-mediated mitophagy in acute kidney injury." (PMID 34566674, 2021). "Studies show that HIF1α plays exerts a protective role in acute kidney injury." (PMID 34481475, 2021). "Moreover, studies have corroborated that HIF1α-mediated mitophagy plays a beneficial role in acute kidney injury by inhibiting tubular cell apoptosis and ROS production." (PMID 35186974, 2021). "HIF-1α knockout attenuates mitophagy, exacerbating ROS accumulation and apoptosis in acute kidney injury (AKI), whereas BNIP3 overexpression rescues this phenotype, highlighting its cytoprotective role." (PMID 40723842, 2025). "Four-and-a-half LIM domains protein 2 (FHL2) is an adaptor protein that may interact with hypoxia inducible factor 1α (HIF-1α) or β-catenin, two pivotal protective signaling in acute kidney injury (AKI)." (PMID 38814462, 2024). "In the pathophysiology of acute kidney injury (AKI), hypoxia-inducible factor (HIF-1α) is expressed in renal tubular cells and can increase the secretion of IL-22 through the activation of CD4+ T cells, thereby regulating glucose metabolism and increasing glycogen storage." (PMID 35432360, 2022).
acute kidney injury (continued). "Hypoxia-inducible factor-1α (HIF-1α)-BNIP3-mediated mitophagy in renal tubular cells attenuates apoptosis and senescence during acute kidney injury (AKI)." (PMID 39456203, 2024). "The biological implications of MAGED2’s role in amplifying hypoxic induction of HIF-1α are broad because MAGED2 is expressed in many adult tissues where it could play a critical role under hypoxic conditions (i.e., high altitude, inflamed hypoxic tissue, acute kidney injury, and cancer)." (PMID 36359819, 2022).
esophageal cancer (40 papers, 2007 to 2025). A primary or metastatic malignant neoplasm involving the esophagus. "Combined VHL/HIF1A inactivation in breast and esophageal cancer cells can also provide resistance to ARV-771, a VHL-based bromodomain degrader that has anti-cancer activity." (PMID 41420106, 2025). "Recent investigations reported that HIF-1α/VEGF pathway contributed to esophageal cancer development." (PMID 38429756, 2024). "Dihydroartemisinin elevated the sensitivity of photodynamic therapy via NF-κB/HIF-1α/VEGF pathway in esophageal cancer cell." (PMID 38429756, 2024). "In summary, our investigation demonstrates that the hypoxia microenvironment can induce HIF1α-dependent RBBP7-mediated up-regulation of CDK4 to promote the progression of esophageal cancer." (PMID 35538026, 2022). "It is also confirmed that HIF-1α has a direct regulatory effect on the transcription of SP1 in esophageal cancer." (PMID 31892989, 2020). "The role of SP1 in HIF-1α-regulated migration and invasion of esophageal cancer cells were then investigated using complementation assays." (PMID 31892989, 2020). "This study showed that the HIF-1α protein level was higher in cancer tissues than in adjacent normal tissues, and the expression of HIF-1α was correlated with tumor metastasis, recurrence and poor prognosis in patients with esophageal cancer." (PMID 31892989, 2020). "For the study of HIF-1α functions in esophageal cancer development, samples of cancer tissues and adjacent normal tissues were collected from 182 patients with ESCC." (PMID 31892989, 2020). "In esophageal carcinoma cells, knock-down of HIF1α inhibited vasculogenic mimicry and HIF1α was shown to upregulate VE-cadherin expression." (PMID 26584646, 2015). "Studies on epithelial ovarian tumors and esophageal cancer showed that HIF-1α overexpression correlated with tumor apoptosis and patient survival." (PMID 23289374, 2013). "Recently, HIF-1a was also found to have a possible role in tumor lymphangiogenesis through the regulation of VEGF-C in human esophageal cancer." (PMID 18190720, 2008). "Similarly, HIF-1α siRNA decreases MMP-2 expression in esophageal cancer Eca109 cells in a hypoxic model with CoCl2 at 6, 12, and 24 h." (PMID 38069210, 2023). "Hence, MMP-2 and E-cadherin expression can be regulated by HIF-1α through Snail, favoring invasion and metastasis of esophageal cancer cells under hypoxic conditions." (PMID 38069210, 2023). "Hypoxia-induced HIF1α could up-regulate RBBP7/CDK4 to promote esophageal cancer progression, which might be considered as a treatment option." (PMID 35538026, 2022). "It has been reported that HIF-1α regulates the expression of various target genes as transcription factor, therefore it is likely that its function in promoting metastasis of esophageal cancer is also working through the activation of downstream target gene transcription." (PMID 31892989, 2020). "HIF-1α also induced the expression of VE-cadherin and modulated VM in esophageal carcinoma cells." (PMID 28320399, 2017). "VE-cadherin was also up-regulated by HIF-1α in esophageal carcinoma." (PMID 28320399, 2017). "Most recent studies reported that downregulated miR-138 sustained inflammatory factor NF-kB activation and promoted esophageal cancer progression, and that miR-138 response to pro-inflammatory cytokines depends on the stabilization of HIF1-α in primary human microvascular endothelial cells." (PMID 24941171, 2014). "Artesunate can promote the degradation of hexokinase 1 (HK1) by targeting it, while simultaneously downregulating the levels of HIF1α and PKM2, thereby inhibiting aerobic glycolysis in esophageal cancer progression." (PMID 40758729, 2025). "In esophageal cancer, NSD1 upregulates HIF-1α expression in collaboration with STAT3, which in turn promotes HIF-1α–driven VEGF signaling and subsequent angiogenic processes." (PMID 41301842, 2025).
esophageal cancer (continued). "Immunohistochemistry staining for PGK1 and HIF‐1α protein was performed on consecutive sections of clinical samples from Stage I and Stage III esophageal cancer patients." (PMID 40534132, 2025). "RBBP7 was identified and experimentally verified to be directly targeted by HIF1α to up-regulated CDK4 in hypoxia conditions to promote viability, proliferation, and stemness of esophageal cancer cells." (PMID 35538026, 2022). "We conclude that hypoxia induces high expression of RBBP7 which is at least partially mediated by HIF1α, up-regulates the expression of downstream CDK4, and thereby promotes tumor progression in esophageal cancer cells." (PMID 35538026, 2022). "Hypoxia-induced HIF1α up-regulates RBBP7 expression, which promotes esophagus cancer cell viability, proliferation, and stemness with increased cyclin-dependent kinase 4 (CDK4) expression." (PMID 35538026, 2022). "In summary, this study has found that HIF-1α and SP1 are highly expressed in esophageal cancer tissues and the expression levels of these two are positively correlated." (PMID 31892989, 2020). "There was a positive correlation between the expression of HIF-1α and SP1 in esophageal cancer tissues (R=0.5388 P <0.0001)." (PMID 31892989, 2020). "In malignant peripheral nerve tumours, STAT3 and HIF-1α promote oncogenic phenotypes, similarly to oesophageal cancer, where STAT3 knockdown was sufficient to block the expression of HIF-1α." (PMID 31947710, 2020). "Also, there is a correlation between HIF1A and immune cells (B cell, CD8+ cell, CD4+ cell, macrophage, neutrophil, or dendritic cell) in esophageal carcinoma, stomach adenocarcinoma, colon adenocarcinoma, and rectum adenocarcinoma." (PMID 39928794, 2025). "Moreover, in esophageal cancer, human esophageal cancer cells showed a reduction in HIF-1α in c-Myc knockdown cells but increased HIF-1α when c-Myc was upregulated, suggesting that c-Myc can facilitate the accumulation of HIF-1α." (PMID 36879346, 2023). "Furthermore, in esophageal cancer, ANXA2 expression was overexpressed and promoted the tumor progression by activating the MYC/HIF1A/VEGF signaling pathway." (PMID 35977942, 2022). "Mechanistic analysis revealed that hypoxia-induced HIF1α could up-regulate RBBP7 to promote the expression of downstream CDK4, thereby enabling the tumor progression of esophageal cancer cells." (PMID 35538026, 2022). "Based on hTFtarget database, HIF-1α is a transcriptional factor for E2F7, which may explain the hypoxia-induced E2F7 in esophagus cancer cells." (PMID 35840974, 2022). "In addition, HIF-1α, bound to the SP1 promoter, regulated SP1 transcription, thereby inducing changes in migration and invasion abilities of esophageal cancer cells." (PMID 31892989, 2020). "Eca109 and KYSE450 esophageal cancer cell lines were cultured under normoxia, hypoxia, or CoCl2-induced hypoxia conditions, which were further transfected with plasmids expressing RB binding protein 7 (RBBP7), hypoxia-inducible factor 1 (HIF1)-α, or RBBP7 shRNA." (PMID 35538026, 2022). "The late expression of HIF-1α and HIF-2α, key mediators of gene induction in response to hypoxia, suggests that hypoxia might not be a key factor driving oesophageal cancer development." (PMID 17437013, 2007).
chronic kidney disease (39 papers, 2014 to 2026). Impairment of the renal function secondary to chronic kidney damage persisting for three or more months. "HIF-1α is associated with chronic kidney disease (CKD) progression and kidney fibrosis by activating the TGF-β1-dependent pathway and mediating the epithelial–to–mesenchymal transition." (PMID 34575914, 2021). "Indeed, hypoxia is a prominent pathophysiological feature of acute kidney injury and chronic kidney diseases that have been associated with increased HIF-1α and/or HIF-2α expression." (PMID 40097388, 2025). "This study was performed with the focus on the association of NCOAs with HIF-1α in the serum of chronic kidney disease (CKD) patients." (PMID 32884936, 2020). "The upregulation of HIF-1α in the models of chronic kidney disease also resulted in NOTCH-1 activation which is known for its profibrotic effect in the kidney." (PMID 39648258, 2025). "The profibrotic role of HIF-1α has been extensively described in numerous animal models of chronic kidney diseases." (PMID 40469714, 2025). "Shen Shuai II Recipe significantly reduced RIF and downregulated the expression of HIF-1α, c-Myc, and IL-1β proteins in 5/6 (A/I) rats with chronic renal failure." (PMID 34211565, 2021). "In animal models, HIF-1α expression level seems to reflect acute renal injury-to-chronic kidney disease (AKI-to-CKD) transition." (PMID 33628631, 2021). "HIF activation through myeloid cell Vhl deletion reduced inflammation in a model of chronic kidney disease, and macrophage HIF-1α deletion increased the immune response to cancer through de-repression of infiltrating cytotoxic T-cell activity." (PMID 31800592, 2019). "It has been reported that HIF-1α exerted an effect in hypoxia- and chronic kidney disease-induced fibrosis, while genetic knock-down of HIF-1α in renal epithelial cells led to a significant reduction in collagen deposition, including COL1A1 and COL3A1." (PMID 30536131, 2019). "Changes in serum biochemical parameters associated with diabetic glomerular injury and progression of chronic kidney disease were more significant in diabetic Hif1α+/− compared to diabetic Wt mice." (PMID 28774305, 2017). "For example, in the specific pathway where the C-terminal transactivation domain of HIF-1α promotes the progression of AKI to chronic kidney disease, the presence of unknown intermediate steps or synergistic factors remains to be elucidated." (PMID 41602837, 2026). "Chronic kidney disease is characterized by upregulation of HIF-1α, but down-regulation of HIF-2α." (PMID 37374094, 2023). "The function of HIF-1α in the development of chronic kidney disease is disputed." (PMID 36297636, 2022). "In mouse models of IRI, sustained HIF-1α activation is associated with severe AKI and fibrosis, whereas administration of the HIF-1α inhibitor PX-478 ameliorates the transition from AKI to chronic kidney disease (CKD)." (PMID 41602837, 2026). "Given the critical role of HIF-1α in tubulointerstitial fibrosis and chronic kidney disease (CKD), a robust appreciation of the role of tubular ROCK will be required in future." (PMID 33150249, 2020). "Studies have indicated that changed expression of hypoxia-inducible factor-1α (HIF-1α) in epithelial cells from the kidney could affect the renal function in chronic kidney disease (CKD)." (PMID 31623681, 2019). "We assessed cat plasma and urine HIF-1α (pHIF-1α/uHIF-1α) concentrations and urine NTBI (uNTBI) concentrations to investigate their relationship with chronic kidney disease (CKD) severity." (PMID 39748872, 2024). "There is evidence that HIF1A can directly regulate and inhibit the expression of Collagen 4 subunit A2 (COL4A2) in renal cells, which can be used to treat acute kidney injury and protect against chronic kidney disease (CKD)." (PMID 35721542, 2022).
osteoporosis (39 papers, 2014 to 2026). A condition of reduced bone mass, with decreased cortical thickness and a decrease in the number and size of the trabeculae of cancellous bone (but normal chemical composition), resulting in increased fracture incidence. "Resveratrol mitigates osteoporosis caused by high-altitude hypoxia by suppressing the ROS/HIF-1α signaling pathway to inhibit osteoclastogenesis." (PMID 40243497, 2025). "Existing studies have reported the association between the HIF-1α signaling pathway and osteoporosis." (PMID 38931373, 2024). "In vivo experiments showed that 2′′-O-RhamnosylIcariside II can exert an anti-osteoporosis effect by alleviating bone loss, promoting bone formation, and inhibiting HIF-1α protein expression." (PMID 38931373, 2024). "HIF1A, a critical factor in bone homeostasis, has been implicated in both the maintenance of bone balance and the development of osteoporosis." (PMID 37875547, 2023). "Hypoxia and HIF-1α have been associated with numerous metabolic bone disorders, including osteoporosis, osteonecrosis and disorders that impact osteoclast differentiation." (PMID 37513651, 2023). "A total of 27 target proteins were obtained, including CD31, EMCN, VEGF, AT1, AT2, ACE, and HIF-1a, all of which are involved in the pathological process of osteoporosis and bone loss and are the target proteins on which MQEP produces a marked effect." (PMID 36147560, 2022). "The hypoxia-inducible factor 1-α (HIF1α), a key molecule in mediating bone-vessel crosstalk, has been considered a promising target for treating osteoporosis caused by gonadal hormones." (PMID 35123567, 2022). "A recent study has demonstrated that HIF-1α was linked to glucocorticoid-induced osteoporosis in mice." (PMID 32047474, 2019). "SERMs act as inhibitors of Hif1α, a therapeutic target of post-menopausal osteoporosis, in osteoclasts under an estrogen-deficient condition." (PMID 27802325, 2016). "However, in estrogen-deficient conditions following menopause onset, HIF1α expression and activity increases, promoting osteoclastic bone resorption and leading to osteoporosis development." (PMID 40004668, 2025). "We speculated that the protective effects of CIHH on osteoporosis induced by SCI might be associated with the regulation of HIF-1α and its downstream factors." (PMID 37229453, 2023). "Thus, all these results imply that HIF-1α signaling in B cells is required for estrogen deficiency-induced osteoporosis by regulating B cell-derived RANKL production." (PMID 35177582, 2022). "With genetic editing or pharmacological methods used to change HIF1α expression, multiple pathological bone metabolism diseases are attenuated, including oral periapical lesions, osteoporosis caused by estrogen or androgen deficiency, pathologic bone fractures and cranial defects." (PMID 35123567, 2022). "Our results suggested that SAL may serve as a good candidate for preventing and treating osteoporosis associated with the activation of HIF-1α-VEGF signalling pathways." (PMID 27558909, 2016). "Furthermore, our previous analysis of ovariectomized (OVX) mice indicated that hypoxia inducible factor 1 alpha (Hif1α) is required for osteoporosis development under an estrogen-deficient condition." (PMID 27802325, 2016). "Resveratrol prevented high-altitude hypoxia-induced osteoporosis by promoting osteoblastogenesis and inhibiting osteoclastogenesis via ROS/HIF-1α suppression." (PMID 40243497, 2025). "On the other hand, pharmacologic treatment with a HIF-1α inhibitor resulted in protection of trabecular and cortical bone from disuse-induced osteoporosis." (PMID 41227294, 2025). "Glucocorticoid-induced osteoporosis is treated by regulating the adenosine monophosphate-activated protein kinase/mTOR and HIF-1α/VEGF signaling pathways." (PMID 40025573, 2025).